NUP153 (nucleoporin 153)
Diseases named in the same sentence as NUP153 in open-access papers (continued):
Sharing a sentence is not in itself a finding about the gene and the disease.
laminopathies (2 papers, 2019 to 2025). "LINC destruction can cause impaired force transmission to the nuclear basket, and basket molecular structures, such as Nup153 and Tpr, are likely to be the primary cause of laminopathies." (PMID 31354529, 2019). "Interestingly, Lamin A mutations in fibroblasts isolated from laminopathy patients exhibit selective disruption in Nup153 binding to both A-type and B-type lamins, resulting in impaired Nup153 localization to the NE and elevated Nup153 enrichment in the nucleoplasm." (PMID 39827403, 2025). "This suggests that Nup153 has a role in the etiology of laminopathies." (PMID 31354529, 2019).
acute myeloid leukaemia (1 paper, 2010). "CBP has been reported to interact directly with nucleoporins NUP98 and NUP153 via the FG repeats, which also mediate its interaction with NUP98-HOXA9 fusion protein associated with acute myeloid leukaemia." (PMID 20006587, 2010).
amyotrophic lateral sclerosis (1 paper, 2025). Amyotrophic lateral sclerosis (ALS) is a neurodegenerative disease characterized by progressive muscular paralysis reflecting degeneration of motor neurons in the primary motor cortex, corticospinal tracts, brainstem and spinal cord. "In amyotrophic lateral sclerosis (ALS) and FTD, the misassemblage of nucleoporins, including NUP98 and NUP153, is observed." (PMID 40868276, 2025).
asthma (1 paper, 2023). "Our hypothesis brings together disparate studies on RV, asthma and Nup153 with the aim to prompt new research into the role of RV infection in development of asthma." (PMID 38249483, 2023). "Future research could investigate the relationship between Nup153 function, TGF-β signaling and development of asthma in models where Nup153 is either downregulated or knocked out." (PMID 38249483, 2023). "We hypothesize that the cleavage of Nup153 in RV infection leads to accumulation of TGF-β induced SMAD2 in the nucleus and sustained AR associated gene expression, essentially priming the airway to increased risk of asthma in later years." (PMID 38249483, 2023).
Benign Prostate Hyperplasia (1 paper, 2018). "When we analysed Nup153 expression by confocal microscopy we found that in the unstimulated conditions Nup153 protein level was higher in PCa cells (C38IM and C27IM) as compared to Benign Prostate Hyperplasia (BPH) cells (C17IM)." (PMID 29963256, 2018).
brain cancer (1 paper, 2025). A primary or metastatic malignant neoplasm affecting the brain. "For NUP153, consistent effects were observed across various brain tissue samples within GTex but did not extend to TCGA brain tumors, possibly due to normal-cancer tissue differences and/or due to that glioma brain cancers originate from glia rather than neurons." (PMID 41023738, 2025).
breast carcinoma (1 paper, 2018). "Nup153 knockdown has been previously linked to alteration of the nuclear lamin A in breast cancer cells." (PMID 29963256, 2018).
breast tumour (1 paper, 2018). "Nucleoporin 153 (Nup153), key regulator of nuclear import/export, has been recently associated to oncogenic properties in pancreatic and breast tumour cells modulating either cell motility and migration or gene expression by chromatin association." (PMID 29963256, 2018).
chronic myeloid leukemia (1 paper, 2021). "To generate hypomorphic alleles of essential genes, we first sought to confirm the essentiality of candidates NUP58, NUP153, and NUP85 in the human chronic myeloid leukemia near‐haploid cell line HAP1." (PMID 34528284, 2021).
gastric cancer (1 paper, 2025). A primary or metastatic malignant neoplasm involving the stomach. "To further validate the association between NUP153 and gastric cancer, we conducted an external validation using human gastric cancer tissue samples." (PMID 40607419, 2025). "We found that NUP153 is highly expressed in several cancers, including gastric cancer, and is closely linked to tumour cell proliferation, changes in the immune microenvironment, and resistance to chemotherapy." (PMID 40607419, 2025). "In particular, the high expression of NUP153 in gastric cancer may be associated with tumour progression, offering a new direction for future clinical strategies." (PMID 40607419, 2025). "The results showed that NUP153 protein expression was significantly higher in gastric cancer tissues than in the surrounding normal tissues." (PMID 40607419, 2025). "The high expression of NUP153 in the brain, oesophagus, and gastric cancer tissues likely indicates a stronger dependence of these organs’ tumours on NUP153 functions, further supporting its organ-specific characteristics." (PMID 40607419, 2025). "Second, although the expression pattern of NUP153 in gastric cancer was validated experimentally, the sample size used was limited." (PMID 40607419, 2025). "Our findings indicate that NUP153 is a critical factor in multiple cancers, especially gastric cancer, where its elevated expression holds promise as a diagnostic and prognostic biomarker." (PMID 40607419, 2025). "Specifically, the study primarily examines the expression characteristics of NUP153 in gastric cancer cells and further verifies the protein expression of NUP153 in gastric cancer tissues through experiments." (PMID 40607419, 2025). "Especially Myc Targats V1 and Complex I. These findings reveal the potential mechanistic role of NUP153 in gastric cancer." (PMID 40607419, 2025). "Additionally, NUP153 expression in gastric cancer tissues was validated using immunohistochemistry and RT-qPCR." (PMID 40607419, 2025). "Further exploration of NUP153-targeted strategies could contribute to the development of more effective and personalised treatments for gastric cancer." (PMID 40607419, 2025). "Taken together, these results suggest that NUP153 may serve not only as a biomarker for gastric cancer diagnosis or prognosis, but also as a viable molecular target for therapeutic intervention." (PMID 40607419, 2025). "Therefore, we propose that targeting NUP153 could become a potential therapeutic strategy to specifically eliminate high-proliferation mucous cell subpopulations and delay gastric cancer progression." (PMID 40607419, 2025). "Notably, the high expression of NUP153 in specific cells suggests that its function is cell-state dependent, which may make it a potential marker for gastric cancer subtyping." (PMID 40607419, 2025). "The results showed that NUP153 expression was significantly higher in gastric cancer tissues than in adjacent non-cancerous tissues (p < 0.05)." (PMID 40607419, 2025). "Immunohistochemistry was employed to detect NUP153 protein expression and compare its levels between gastric cancer tissues and adjacent non-cancerous tissues." (PMID 40607419, 2025). "We also focused on NUP153 expression in gastric cancer and used immunohistochemistry to analyse the expression levels of NUP153 in gastric cancer tissues and adjacent non-cancerous tissues." (PMID 40607419, 2025). "Finally, through experimental verification, we analysed the expression levels of NUP153 protein in gastric cancer tissues and adjacent non-cancerous tissues." (PMID 40607419, 2025). "Additionally, RT-qPCR was used to detect NUP153 mRNA expression, confirming that its levels were significantly higher in gastric cancer tissues compared to non-cancerous tissues (p < 0.05)." (PMID 40607419, 2025).
gastric cancer (continued). "Furthermore, our study also conducted an in-depth analysis of single-cell data from gastric cancer, comparing the biological characteristics of NUP153-positive and negative expression groups." (PMID 40607419, 2025). "In gastric cancer, NUP153 was markedly upregulated compared to adjacent non-cancerous tissues." (PMID 40607419, 2025).
hepatocellular carcinoma (1 paper, 2024). A malignant tumor that arises from hepatocytes. "For instance, high expression levels of human nucleoporin NUP153, which facilitates nucleocytoplasmic transport, occur in hepatocellular carcinoma (HCC), probably leading to alterations in NPC composition and function." (PMID 39080077, 2024).
Hutchinson-Gilford progeria syndrome (1 paper, 2022). "Most remarkably, progerin, a progeriatric isoform of Lamin A and causing the Hutchinson-Gilford progeria syndrome in humans, displaces Nup153 and TPR (the mammalian homologs of Nup60 and Mlp1/2) from the nuclear periphery." (PMID 35373738, 2022).
influenza infection (1 paper, 2021). "From MAGMAv1.07b, we identified three significant genes with a primary role in influenza infection: FGFR2, KPNB1 and NUP153." (PMID 33924631, 2021).
leukemia (1 paper, 2025). A malignant (clonal) hematologic disorder, involving hematopoietic stem cells and characterized by the presence of primitive or atypical myeloid or lymphoid cells in the bone marrow and the blood. "Analysis of key factors, including Pol II, H3K27ac, BPTF, K/C, and MLL, in K/C-III leukemia cells revealed that A485 treatment for 6 h significantly decreased chromatin accessibility, Pol II loading, and the recruitment of the KAT6A-NURF-MLL module at Nup153 and Hoxa cluster loci." (PMID 40830799, 2025).
lupus (1 paper, 2008). "Nup153 is a nucleoporin and an autoantibody target in lupus." (PMID 19578517, 2008).
ovarian carcinoma (1 paper, 2010). A malignant neoplasm originating from the surface ovarian epithelium. "Northern blots for importin B1 and Nup153 confirmed that ovarian carcinoma and HIO cells contained increased message levels for these genes compared to normal HOSE cells (not shown)." (PMID 20174585, 2010).
pancreatic cancer (1 paper, 2013). "Most notably, the analysis also revealed novel possible oncogenic functions of nucleoporin NUP153 (ostensibly by modulating TGFβ signaling) and Kruppel-like transcription factor KLF5 in pancreatic cancer." (PMID 24041470, 2013).
paraganglioma (1 paper, 2025). A benign or malignant neoplasm arising from paraganglia located along the sympathetic or parasympathetic nerves. "Preclinical validation showed that X4.5dianilinophthalimide significantly suppressed NUP153 activity in adrenal cortical carcinoma (ACC), pheochromocytoma and paraganglioma (PCPG), and READ, while Imatinib exhibited similar inhibitory effects in STAD." (PMID 40607419, 2025).
poliovirus infection (1 paper, 2021). An disease or disorder caused by infection with Enterovirus C. "Later, it was shown that another FG-nucleoporin, NUP98, was also degraded during poliovirus infection, but at an earlier time of infection (around 2 h.p.i compared to 4 h.p.i for NUP153 and NUP62)." (PMID 34201715, 2021).
renal clear cell carcinoma (1 paper, 2025). "Specifically, in kidney in renal clear cell carcinoma(KIRC), NUP153 was a protective factor for prognosis, whereas in renal papillary carcinoma (KIRP), sarcoma (SARC), and UCEC, NUP153 was a risk factor for prognosis." (PMID 40607419, 2025).
retinoblastoma (1 paper, 2014). A malignant tumor that originates in the nuclear layer of the retina. "We did observe subtle elevation in the expression of DEK, NUP153, E2F3 and TTRAP and additional studies will be required to determine the functional significance of elevated gene expression in human retinoblastoma." (PMID 24509483, 2014).
sarcoma (1 paper, 2025). A usually aggressive malignant neoplasm of the soft tissue or bone. "High NUP153 expression was linked to tumour-associated macrophage infiltration and correlated with poor prognosis in some cancers like Kidney Renal Papillary Cell Carcinoma and Sarcoma." (PMID 40607419, 2025).
squamous cell carcinoma (1 paper, 2024). A carcinoma arising from squamous epithelial cells. "Through this perspective, NUP153 could be viewed as a strong ringmaster in gene expression regulation that exerts a critical impact on the p63 (TP63) transcription factor associated with squamous cell carcinoma tumorigenesis." (PMID 39000572, 2024). "NUP153 is also involved in the mechanism that regulates p63 expression, making it highly relevant to squamous cell carcinoma." (PMID 39000572, 2024).
thyroid tumor (1 paper, 2021). A benign or malignant neoplasm affecting the thyroid gland. "Moreover, experimental validation confirmed that NUP153 and USB1 impact the growth of thyroid tumor cell lines." (PMID 33816259, 2021).
varicocele (1 paper, 2021). A condition characterized by the dilated tortuous veins of the spermatic cord with a marked left-sided predominance. "Considering the role of NUP153 in DNA repair response and its binding with other NUPs as NPC components, we can speculate that NUP93 might be involved in this type of cellular regulation, explaining why our in silico analysis predicted downregulation of NUP93 in varicocele patients." (PMID 34975746, 2021).
ZIKV infection (1 paper, 2020). "We found that while during DENV infection the integrity and distribution of at least three nucleoporins (Nup), Nup153, Nup98, and Nup62 were altered, during ZIKV infection, the integrity of TPR, Nup153, and Nup98 were modified." (PMID 32466480, 2020). "The distribution and integrity of Nup153 were also determined during ZIKV infection." (PMID 32466480, 2020). "Our results indicate that during DENV infection, the integrity and distribution of at least Nup153, Nup98, and Nup62 were disrupted, while during ZIKV infection, the integrity of TPR, Nup153, and Nup98 were altered." (PMID 32466480, 2020).
infection (31 papers, 2011 to 2025). The state of being infected such as from the introduction of a foreign agent such as serum, vaccine, antigenic substance or organism. "HIV-1 with mutations in CA that prevent interaction with soluble factors such as CPSF6 and CypA, exhibit a differential dependence on Nups during infection, including loss of reliance on both Nup153 and Nup358." (PMID 37355754, 2023). "PF74 has bimodal inhibition kinetics, in which at low concentrations it reduces infection by competing with cofactors Nup153 and CPSF6 while at high concentrations it causes irreversible and catastrophic uncoating that prevents reverse transcription." (PMID 31851928, 2019). "Others have previously shown that binding of HIV-2ROD CA and HIV-1 CA to Nup153 is required for optimal infection, especially in association to four residues, N56, Q66, R69, N73 in HIV-2ROD CA77." (PMID 28345672, 2017). "In contrast, if Nup153 helps maintaining capsid at the viral core, its depletion should result in more shedding of capsid and lower susceptibility to TRIMCyp restriction (greater rescue of infection)." (PMID 27107820, 2016). "In summary, co-depletion of LEDGF, ADAM10 and Nup153 replicated the effects, in terms of modulation of susceptibility to infection and viral DNA detection, observed through increased levels of miR-155 both in the context of TLR3 stimulation and ectopic expression in primary human MDMs." (PMID 23028330, 2012). "Two distinct effects on infection are observed when CypA is depleted in Nup153- and Nup155-knockdown cells." (PMID 37355754, 2023). "In order to investigate nuclear entry of the A14C/E45C mutant further, we monitored the interactions between CA and the nuclear pore proteins NUP358 and NUP153 during infection." (PMID 34543344, 2021). "It was surprising, therefore, that while NUP153 depletion reduced HIV-1WT infection of HeLa and HOS cells, the effect of NUP153 depletion on HIV-1WT infection of HT1080 cells was marginal." (PMID 30084827, 2018). "The HIV-1 requirements for TNPO3, NUP358, and NUP153 mapped to the nuclear steps of infection, either preceding or concomitant with integration." (PMID 24103892, 2013). "We observed a moderately strong inverse correlation between requirement for NUP153 and cell cycle dependence during infection." (PMID 24130490, 2013). "In agreement with others’ results, we found that both HIV-1 and HIV-2ROD infection of Nup153 knockdown HEK-293T cells was significantly inhibited while HIV-1 G89V infection remained unaffected as compared to the infection of control cells." (PMID 23883001, 2013). "Resembling our observations with NUP153 knockdown cells, infection of TNPO3 depleted cells exhibited a similar profile of reduced sensitivity to PF74." (PMID 24130490, 2013). "Proteolysis of these three FG-Nups have different kinetics with cleavage of Nup98 early, followed by Nup62 and Nup153 at later times post-infection, the latter coinciding with a block in import of multiple nuclear proteins." (PMID 23959328, 2013). "Nevertheless, we found that, like HIV-1, human-adapted HIV-2 infection was dependent on Nup358/RanBP2 and Nup153 interactions for optimal infection." (PMID 23883001, 2013). "Correlation between NUP153 binding and dependence on endogenous NUP153 expression additionally support the relevance of this interaction during infection." (PMID 24130490, 2013). "As we predict that mutant viruses that require NUP153 for infection also bind NUP153C, we compared the sensitivities of CA mutant viruses to NUP153 knockdown with their susceptibility to Trim-NUP153C mediated restriction." (PMID 24130490, 2013). "As the N74D mutation clearly counteracts CPSF6 binding, it seems plausible that CPSF6 engagement licenses HIV-1 to employ NUP358 and NUP153 during infection." (PMID 24103892, 2013). "We observed that CA mutant viruses that require endogenous NUP153 for infection were also sensitive to Trim-NUP153C mediated restriction." (PMID 24130490, 2013).